ANKLE2 (ankyrin repeat and LEM domain containing 2)
Description:
Involved in mitotic nuclear envelope reassembly by promoting dephosphorylation of BAF/BANF1 during mitotic exit. Coordinates the control of BAF/BANF1 dephosphorylation by inhibiting VRK1 kinase and promoting dephosphorylation of BAF/BANF1 by protein phosphatase 2A (PP2A), thereby facilitating nuclear envelope assembly. May regulate nuclear localization of VRK1 in non-dividing cells. It is unclear whether it acts as a real PP2A regulatory subunit or whether it is involved in recruitment of the PP2A complex. Involved in brain development.
Synonyms: KIAA0692; LEM4; LEMD7; MCPH16
Tractability: Antibody: UniProt predicts a signal peptide or a membrane-spanning region. PROTAC: ubiquitination databases record sites on it; its protein half-life has been measured.
Gene: Protein-coding gene on chromosome 12 (132,725,503 to 132,761,832, reverse strand). Ensembl gene ENSG00000176915.
Subcellular location: Endoplasmic reticulum membrane
Subcellular location (Human Protein Atlas): Plasma membrane; Endoplasmic reticulum
Pathways (Reactome):
Signal Transduction: RAC2 GTPase cycle; RHOG GTPase cycle
Cell Cycle: Initiation of Nuclear Envelope (NE) Reformation
Gene Ontology:
Molecular function: protein binding; protein kinase inhibitor activity; protein phosphatase 2A binding; protein phosphatase regulator activity
Biological process: central nervous system development; mitotic nuclear membrane reassembly; negative regulation of apoptotic process; negative regulation of phosphorylation; regulation of catalytic activity; nervous system development; nuclear membrane reassembly
Cellular component: endoplasmic reticulum; endoplasmic reticulum membrane; membrane
Genetic constraint (gnomAD): Loss-of-function variants: 55 observed, 83.41 expected, observed/expected ratio (o/e) 0.66, 90% interval 0.53 to 0.82. The upper end of that interval is the gene's LOEUF score, 0.82, which puts it in group 3 of 6, group 1 being the genes least tolerant of losing a copy. Missense variants: 1,238 observed, 1,188.3 expected, observed/expected ratio (o/e) 1.04, 90% interval 0.99 to 1.09. Synonymous variants: 551 observed, 473.82 expected, observed/expected ratio (o/e) 1.16, 90% interval 1.08 to 1.25.
Homologues: Orthologues: macaque ANKLE2 (95% identical), chimpanzee ANKLE2 (87% identical), pig ANKLE2 (75% identical), rabbit ANKLE2 (71% identical), dog ANKLE2 (71% identical), mouse Ankle2 (70% identical), rat Ankle2 (70% identical), guinea pig ANKLE2 (67% identical), tropical clawed frog ankle2 (53% identical), zebrafish ankle2 (47% identical), Drosophila melanogaster Ankle2 (25% identical), Caenorhabditis elegans lem-4 (20% identical).
Diseases named in the same sentence as ANKLE2 in open-access papers:
ANKLE2 is named in the same sentence as 20 diseases in open-access papers, as found by Europe PMC text mining. Sharing a sentence is not in itself a finding about the gene and the disease. The quoted sentences say what the papers report.
microcephaly (20 papers, 2020 to 2025). A congenital or acquired developmental disorder in which the circumference of the head is smaller than normal for the person's age and sex. "The conserved role of ANKLE2 in replication across hosts and orthoflaviviruses revises our model in which ZIKV NS4A inhibits ANKLE2 to cause microcephaly." (PMID 39804047, 2025). "If these orthoflaviviruses were able to gain access to the developing fetal brain, they also have the potential to cause ANKLE2-dependent microcephaly." (PMID 39804047, 2025). "ANKLE2 function is crucial for the development of the central nervous system as mutations in this gene are associated with microcephaly." (PMID 39964262, 2025). "Humans carrying homozygous or compound heterozygous mutations in either ZNF335 or ANKLE2 exhibit severe microcephaly like that characteristic of Zika patients." (PMID 36202870, 2022). "This patient was born with an extreme microcephaly, so we looked at the brains of flies with a mutation in Ankle2 and they also had very small brains." (PMID 35302163, 2022). "The expression of NS4A in fruit flies heterozygous for a hypomorphic allele of Ankle2 caused a more significant microcephaly in comparison to the condition induced in wild-type fruit flies." (PMID 35269756, 2022). "Ankyrin repeat and LEM domain containing 2 (ANKLE2) has been shown to be associated with hereditary microcephaly, as mutations in ANKLE2 causes microcephaly in humans and Drosophila." (PMID 34696510, 2021). "The microcephaly phenotype caused by ectopic expression of ZIKV NS4A was found to be rescued by ectopic expression of human ANKLE2." (PMID 34696510, 2021). "While Ankle2 impacts the asymmetric division protein machinery, it remains unclear whether the loss of its function in nuclear reassembly also contributes to microcephaly." (PMID 39964262, 2025). "Targeting of Ankle2 by the Zika virus also causes microcephaly." (PMID 39964262, 2025). "Pathogenic mutations in ANKLE2 cause congenital microcephaly in humans (29, –, 31)." (PMID 39804047, 2025). "In addition, in-depth imaging and clinical evaluation of ANKLE2-associated microcephaly in humans revealed twelve additional cases of MCPH16, and new pathogenic ANKLE2 variants located in various domains of ANKLE2." (PMID 38691001, 2024). "Also, ZIKV NS4A has been reported to directly interact with ANKLE2, which is a protein linked to human microcephaly, and disrupt neural stem cell division and brain development." (PMID 37781396, 2023). "Based on the mechanism revealed in this study, it is possible that microcephaly resulting from Zika infection or loss of ZNF335 or ANKLE2 may be driven by cGAS/STING-dependent apoptosis of neuronal progenitors and/ or CNS immune cells." (PMID 36202870, 2022). "ANKLE2 mutation is known to cause autosomal recessive microcephaly in humans." (PMID 36078091, 2022). "Indeed, the ANKLE2 heterozygous mutations in humans are associated with infants’ severe microcephaly and later cognitive, neurological, intellectual and developmental deficits." (PMID 35269756, 2022). "Finally, they identified an interaction between NS4a of ZIKV and ANKLE2, a gene previously associated with microcephaly, and showed that inhibition of ANKLE2 by NS4b likely contributes to the microcephaly induced by ZIKV." (PMID 34064113, 2021). "Additional congenital microcephaly patients who carry deleterious variants in this gene were subsequently identified by several clinical genetic research groups, establishing ANKLE2 as a bona fide microcephaly causing gene in humans." (PMID 33800390, 2021). "This binding might play an important role in the development of microcephaly, as inactivation of ANKLE2 and loss of SMPD4, which encodes a neutral sphingomyelinase that produces ceramide in the ER, all leads to development of the disease." (PMID 34793833, 2021). "Similarly, in humans, ANKLE2 has been linked to hereditary microcephaly." (PMID 40940714, 2025).
microcephaly (continued). "Thus, loss of ANKLE2 as a result of microcephaly-associated genes or congenital infection may contribute to microcephaly by impacting neural cell proliferation or the fate of neurons during development." (PMID 36078091, 2022). "By searching for host proteins with known roles in neurodevelopment or associations with microcephaly, we identified the interaction between ZIKV NS4A and host ankyrin repeat and LEM domain-containing 2 (ANKLE2)." (PMID 39804047, 2025). "Using this Drosophila model, we previously showed that transgenic expression of ZIKV NS4A induces similar microcephaly phenotypes which are also rescued by the expression of human ANKLE2." (PMID 39804047, 2025). "Mutations in ANKLE2 cause congenital microcephaly, and NS4A induces microcephaly in an ANKLE2-dependent manner." (PMID 39804047, 2025). "ZIKV NS4A also targets another microcephaly-related protein ANKLE-2 and thus disrupts neurogenic asymmetric cell division in neural stem cells leading to microcephaly in a drosophila model." (PMID 35412344, 2022). "Associated with brain development; its mutations causes microcephaly; ZIKV-NS4A resulted in reduction of brain size, affected neuroblast division and brain development in Drosophila by targeting the ANKLE2 pathway." (PMID 35371036, 2022). "Another high-profile study used fly models to demonstrate that genetic variants in ANKLE2, a protein linked to hereditary microcephaly, and ZIKV protein NS4A which interacts with and inhibits Ankle2 protein function, converge on the same pathological pathways." (PMID 33766136, 2021). "Using a fruit fly model, we showed that NS4A induced microcephaly in an ANKLE2-dependent manner." (PMID 39804047, 2025). "Our study also revealed that NS4A from non-teratogenic orthoflaviviruses can physically interact with ANKLE2, although these viruses do not cause microcephaly in humans." (PMID 39804047, 2025). "However, ANKLE2’s unique role in ZIKV NS4A-induced microcephaly is a consequence of ZIKV infection of important developing tissues in which ANKLE2 has essential roles." (PMID 39804047, 2025). "Overall, this suggests NS4A induces microcephaly in vivo in an ANKLE2-dependent manner." (PMID 39804047, 2025). "In drosophila, NS4A induces microcephaly by inhibiting the host protein Ankle2 and its pathway." (PMID 39621753, 2024). "Moreover, a recent study reported that Ankle2 knock-out in zebrafish resulted in microcephaly and a decrease in the number of radial glial progenitor cells, suggesting a role in neurogenesis in this model." (PMID 39621753, 2024). "In humans, pathogenic loss-of-function mutations in ANKLE2 are associated with primary congenital microcephaly, a condition in which the brain is not properly developed at birth." (PMID 38691001, 2024). "In addition, ANKLE2 was identified as a key molecule which can contribute to neuroblast development and microcephaly in humans." (PMID 37781396, 2023). "This mutant phenotype was rescued by wild-type ANKLE2 but not by a microcephaly-associated ANKLE2 variant (ANKLE2Q782X)." (PMID 35269756, 2022). "Co-expression of ZIKV NS4A with hANKLE2 or dAnkle2 rescued this phenotype, but not with the microcephaly-associated hANKLE2 variant (hANKLE2 Q782X), indicating that ANKLE2 is protective against ZIKV-driven neuropathology." (PMID 36078091, 2022). "Their study identified a Zika protein, NS4A, that robustly binds to ANKLE2, but they had no idea if this interaction was related to the microcephaly associated with the Zika virus epidemic in South America." (PMID 35302163, 2022). "They elegantly demonstrate that Ankle2 interaction with Ballchem/VRK1 regulates asymmetric protein localization during neuroblast division, and that disruption of this pathway leads to microcephaly in both human patients due to genetic causes and flies induced by ZIKV infection." (PMID 33766136, 2021).
microcephaly (continued). "This suggests that typically non-pathogenic variation in ANKLE2 may sensitize individuals to ZIKV-induced microcephaly, tipping the scales from haplosufficiency to haploinsufficiency." (PMID 38691001, 2024). "Interestingly, this defect could be rescued by co-expression of wild-type fly Ankle2 or reference (wild-type) human ANKLE2, suggesting that NS4A is acting through ANKLE2 to cause microcephaly in flies." (PMID 33800390, 2021). "Together, these findings suggest that ZIKV NS4A interacts with the host ANKLE2 to inhibit its functions in cell division, subsequently dysregulating NPC development and leading to microcephaly." (PMID 38691001, 2024). "ZIKV NS4A has been found to physically interact with ANKLE2 in human cells, and ectopic expression of ZIKV NS4A in Drosophila larval brain resulted in microcephaly, increased apoptosis, and reduced proliferation of neuroblasts." (PMID 34696510, 2021). "It was further shown that ZIKV-induced microcephaly is mediated through human Ankryin repeat and LEM domain-containing 2 (ANKLE2)." (PMID 32152180, 2020). "In comparison with ZIKV NS4A, DENV 2 NS4A was shown to interact with ANKLE2 with a lower affinity, without significantly inducing microcephaly, consistent with the fact that DENV does not cause microcephaly in human." (PMID 34696510, 2021).
breast carcinoma (11 papers, 2018 to 2025). "In ESR+ human breast cancer cells ANKLE2 acts as a scaffold by stabilizing and facilitating the phosphorylation of estrogen receptor alpha (ESRα) through aurora-A kinase, thus activating ERα signaling, and increasing DNA binding and transactivation." (PMID 38691001, 2024). "Recently, a novel role was revealed for the Lem domain protein, Ankle2, in breast cancer tumourigenesis." (PMID 36205821, 2022). "They demonstrated that Ankle2 is overexpressed in breast cancer, and this overexpression facilitated breast cancer proliferation and migration." (PMID 36205821, 2022). "ANKLE2 is reported to be overexpressed in breast cancer, and its expression has been shown to positively regulate growth in breast cancer cells." (PMID 34685604, 2021). "Function of ANKLE2 as a mitotic regulator also has implications in ovarian and breast cancer." (PMID 38691001, 2024). "Given the Lem-D transcripts, Ankle2, TMPO, Emerin, and Lemd2, were overexpressed in breast cancer patient samples and overexpression largely associated with poorer patient outcomes, we next investigated whether the Lem-D proteins were similarly overexpressed in TNBC cell lines." (PMID 38720803, 2024). "Altered NE protein expression, including Lamin A/C, Ankle2 and LAP2, is reported in breast cancer models." (PMID 40664994, 2025). "There is evidence to suggest that Ankle2, TMPO, Emerin, and Lemd2 expressions are correlated with breast cancer patient outcomes, but larger patient sample numbers are required to confirm this." (PMID 38720803, 2024). "GENT2, TCGA, and KM plotter were utilized to investigate the expression and prognostic implications of several Lem-D proteins: Ankle2, TMPO, Emerin, and Lemd2 in publicly available breast cancer patient data." (PMID 38720803, 2024). "Similarly, in estrogen receptor-positive (ESR+) human breast cancer cells lines (T47D, BT474 and MCF7), ANKLE2 overexpression contributes to tamoxifen resistance and accelerated tumor growth." (PMID 38691001, 2024). "We demonstrated that Ankle2 transcripts were overexpressed in breast cancer samples, compared to non-cancerous tissue, and the extent of overexpression negatively correlated with breast cancer patient OS." (PMID 38720803, 2024).
autosomal recessive primary microcephaly (3 papers, 2017 to 2022). Autosomal recessive primary microcephaly (MCPH) is a rare genetically heterogeneous disorder of neurogenic brain development characterized by reduced head circumference at birth with no gross anomalies of brain architecture and variable degrees of intellectual impairment. "In another example, a novel disease gene whose biological function was poorly characterized (ANKLE2) was discovered to be linked to autosomal recessive primary microcephaly 16 (MIM# 616681)." (PMID 28874452, 2017). "ZNF335 and ANKLE2 are responsible for regulating the proliferation and differentiation of neuronal progenitor cells, and both are candidate genes of autosomal recessive primary microcephaly, which is characterized by reduced skull circumference and brain volume." (PMID 35456484, 2022).
breast tumor (2 papers, 2018 to 2024). "Ankle2, TMPO, Emerin, and Lemd2 were significantly overexpressed in breast tumor samples, in comparison to adjacent normal tissue." (PMID 38720803, 2024).
tauopathies (2 papers, 2023 to 2024). "ANKLE2 is also linked to other disease pathologies, including congenital Zika syndrome, cancer and tauopathy." (PMID 38691001, 2024). "Intriguingly, gene silencing of ANKLE2 and BANF1 resulted in some of the most potent effects on tau aggregation, yet little is known about the role of these genes in tauopathies." (PMID 36316035, 2023). "Although not as well established, a post-mitotic function of ANKLE2 may also regulate the development of tauopathies." (PMID 38691001, 2024).
Zika (2 papers, 2022 to 2025). "Altogether, these results suggest that our rescue phenotypes would be stronger if ANKLE2 expression were more homogeneously restored and that ANKLE2 supports ZIKV infection in Huh7 cells." (PMID 39804047, 2025). "Depletion of ANKLE2 reduces ZIKV replication in multiple cell lines that represent biologically relevant sites of ZIKV infection." (PMID 39804047, 2025). "Altogether, we report the novel function of ANKLE2 in promoting ZIKV infection, providing evidence that NS4A disruption of neurodevelopment through ANKLE2 may arise from a general underlying mechanism of orthoflavivirus replication." (PMID 39804047, 2025). "Together, we conclude that ANKLE2 likely mediates some aspects of ER rearrangements during ZIKV infection, the dysregulation of which may drive increased immune induction and decreased ZIKV replication." (PMID 39804047, 2025). "Therefore, we evaluated ANKLE2 subcellular localization during ZIKV infection." (PMID 39804047, 2025).
cervical carcinoma (1 paper, 2024). A carcinoma arising from either the exocervical squamous epithelium or the endocervical glandular epithelium. "Furthermore, we demonstrated that siRNA-mediated depletion of Ankle2 induced a markedly abnormal nuclear phenotype in TNBC cells, consistent with prior findings in U-2OS osteosarcoma cells and HeLA cervical carcinoma cells." (PMID 38720803, 2024).
neuroblastoma (1 paper, 2025). Neuroblastoma (NB) is the most common solid, extracranial childhood tumor. "Interestingly, we found that only partial ANKLE2 reduction was required in neuroblastoma SK-N-SH cells to cause a significant impact on virus replication." (PMID 39804047, 2025). "ZIKV replicates in the developing brain, and we therefore examined the role of ANKLE2 in neuroblastoma SK-N-SH cells." (PMID 39804047, 2025).
ovarian carcinoma (1 paper, 2024). A malignant neoplasm originating from the surface ovarian epithelium. "Using RNAi to silence ANKLE2 in various human ovarian cancer cell lines (SKOV3, OVCAR, and APOCC) decreases cell viability and cell migration, and increases chemosensitivity to paclitaxel, a common chemotherapy used in ovarian cancer." (PMID 38691001, 2024).
cancer (6 papers, 2018 to 2025). A tumor composed of atypical neoplastic, often pleomorphic cells that invade other tissues. "We review reported insights into the molecular and cellular functions of ANKLE2 and, finally, explore recent findings that suggest novel roles for ANKLE2 in neurodevelopment, cancer, neurodegenerative diseases, immune system development and virus pathogenesis." (PMID 38691001, 2024). "The Lem-D proteins, including Ankle2, Lemd2, TMPO, and Emerin, have been shown to be associated with many of the hallmarks of cancer." (PMID 38720803, 2024). "Given the role of ANKLE2 in regulating cell division, its altered or inhibited function can lead to severe cellular defects that, ultimately, result in dysregulated neurodevelopment or cancer." (PMID 38691001, 2024). "We show one network consisting of 12 genes including ANKLE2, SHROOM3 and ELFN2 interacting through direct connections with VIRMA, a nuclear/cytosolic protein involved in RNA methylation/adenylation and implicated in different cancers." (PMID 35619151, 2022).